ARF6 (ARF GTPase 6)
Diseases named in the same sentence as ARF6 in open-access papers (continued):
Sharing a sentence is not in itself a finding about the gene and the disease.
intrauterine growth restriction (1 paper, 2012). "An unexpected finding from this paper was the decrease in expression of myometrial ARF6/CYTH3 and ARF6-GTP levels in pregnancies complicated by pre-eclampsia, intrauterine growth restriction or haemorrhage." (PMID 22666423, 2012).
leukemia (1 paper, 2025). A malignant (clonal) hematologic disorder, involving hematopoietic stem cells and characterized by the presence of primitive or atypical myeloid or lymphoid cells in the bone marrow and the blood. "Future studies should employ in vivo models to investigate the consequence of ARF6 manipulation on leukemia initiation, progression, and response to therapy." (PMID 40275490, 2025).
lymphoma (1 paper, 2022). A malignant (clonal) proliferation of B- lymphocytes or T- lymphocytes which involves the lymph nodes, bone marrow and/or extranodal sites. "ARF6 mRNA expression was found to be at low levels in the adrenal gland, breast, cervix, oesophagus, colon and the endometrium, at moderate levels in the lung, lymphoma, bladder, thyroid, stomach, testis, liver and the highest levels in the kidney, prostate, ovary and pancreas." (PMID 35143561, 2022).
malaria (1 paper, 2013). Malaria is a serious and sometimes fatal disease caused by a parasite that commonly infects a certain type of mosquito which feeds on humans. "Gene expression levels were greater than two-fold change in acute febrile malaria including: Fc alpha receptor, Fc gamma receptor 3B, Fc epsilon receptor 1G, PI3K, MAP2K2, Arf6, KLRC3, KIR3DL2, and CEBP gamma (range two- to four-fold)." (PMID 24188121, 2013).
metastatic cancer (1 paper, 2022). A carcinoma which has spread from the original site of growth to another anatomic site. "Although alterations in ARF6 expression and activity have been linked to metastatic cancer in one or two tissues, the expression of ARF6 in cancers over a wide range of tissues has not been studied so far." (PMID 35143561, 2022).
myeloid leukemia (1 paper, 2015). A clonal proliferation of myeloid cells and their precursors in the bone marrow, peripheral blood, and spleen. "Arf6 protein is four to five times more abundant in these myeloid leukemia cells when compared to human PMNs." (PMID 26609537, 2015). "The expression of Arf6 in PMNs and neutrophil-like cells such as differentiated HL-60 or PLB-985 myeloid leukemia cells has been previously reported." (PMID 26609537, 2015).
myeloma (1 paper, 2019). "Based on similar results with an anti-CD38 antibody in myeloma and CSL362 with HL, we infer that our observation of the involvement of ARF6–PLD-1 may be generally applicable in NK-mediated ADCC." (PMID 30647406, 2019).
nephritis (1 paper, 2017). Inflammation of renal tissue. "We investigated ARF6 function in two acute injury models, protamine sulfate perfusion and NTS nephritis." (PMID 28880939, 2017).
oesophageal adenocarcinoma (1 paper, 2022). "We further evaluated ARF6 protein expression in oesophageal adenocarcinoma (EAC) tissue microarray cores by immunohistochemistry." (PMID 35143561, 2022).
orchitis (1 paper, 2021). Inflammation of one or both testes due to viral or bacterial infections. "The data revealed that proinflammatory cytokines were inclined to induce both senescence and apoptosis during orchitis in both Lc and Sg, but the Arf6 pathway displayed a different response towards these cytokines in Lc and Sg." (PMID 35111154, 2021). "Many of these signaling pathways, including the PID Arf6 and PID angiopoietin receptor pathways, were increased in Lc during orchitis." (PMID 35111154, 2021).
overactive bladder (1 paper, 2025). Symptom of overactive detrusor muscle of the urinary bladder that contracts with abnormally high frequency and urgency. "Arf6 and Rac1 may be potentially involved in detrusor overactivity, bladder wall thickening and medical treatment of overactive bladder." (PMID 40332567, 2025).
pulmonary hypertension (1 paper, 2019). Increased pressure within the pulmonary circulation due to lung or heart disorder. "Inhibition of Arf6 activity with cytohesin inhibitors, such as SecinH3, restores BMPRII expression and reduces inflammatory responses in cultured endothelial cells and the lungs of animal models of pulmonary hypertension and prevents development of the disease in preclinical models of PAH." (PMID 30582444, 2019).
serous ovarian cancer (1 paper, 2023).
sterility (1 paper, 2018). "However, their low levels during ovule differentiation and growth are not consistent with the sterility observed in the ARF6–2/ARF8–3 double mutant; additional studies are needed to determine whether ARF6 and ARF8 are enriched in the ovule and modulate its growth." (PMID 29739322, 2018).
Stroke (1 paper, 2023). Sudden impairment of blood flow to a part of the brain due to occlusion or rupture of an artery to the brain. "Conversely, increased transcript expression of Arf6 and Cdc42ep4 was observed in old and young post-stroke BBB." (PMID 36855111, 2023).
tongue SCC (1 paper, 2016). "We here examined whether tongue SCC also express the mesenchymal component of the ARF6-based pathway, namely EPB41L5, and whether its expression correlates with malignancy." (PMID 27871329, 2016).
viral hepatitis (1 paper, 2020). An acute or chronic inflammation of the liver parenchyma caused by viruses. "Among the proteins encoded by these genes, ubiquitin carboxyl-terminal hydrolase 6 (USP6) regulates plasma membrane localization of ADP-ribosylation factor 6 (ARF6), while mucin 6, oligomeric mucus/gel-forming (MUC6) is involved in reactive biliary epithelium in viral hepatitis." (PMID 32848883, 2020).
tumor (98 papers, 2007 to 2026). "In this model, tumor-specific loss of Arf6 significantly reduced tumor growth to a level equivalent to PtenWT tumors (measured from the time of tumor formation), and prolonged overall survival despite the absence of PTEN." (PMID 40909781, 2025). "Given that Arf6 deletion prevented primary tumor acceleration caused by PTEN loss, there is a component of ARF6-dependent survival that is necessary for, and/or functions independently of the PI3K pathway." (PMID 40909781, 2025). "In this review, we provide an overview of the recent insights into the intrinsic and extrinsic roles of ARF6 and its associated signaling machinery in tumor progression." (PMID 37834383, 2023). "Here, we report the first characterization of a well-known antibiotic drug targeting Arf6-associated functions that endow tumor cells with disseminating properties." (PMID 33673086, 2021). "In this current study, ARF6 was critical for tumor growth acceleration caused by loss of PTEN." (PMID 40909781, 2025). "Nevertheless, loss of ARF6 significantly delayed tumor onset in Ptenf/f mice." (PMID 40909781, 2025). "Recently, the role of ARF6 was associated with the tumor microenvironment." (PMID 38533085, 2024). "Moreover, ARF6 expression was associated with tumor invasiveness and detected on MVs released from a set of tumor cell lines." (PMID 36681803, 2023). "Arf6 is involved in angiogenesis and is implicated in tumor metastasis." (PMID 30866419, 2019). "ARF6 and its regulators have been implicated in tumor development and metastasis." (PMID 31792062, 2019). "We subsequently tested whether Egfr/Arf6-triggered Hh signalling synergizes with oncogenic Ras to cause tumour overgrowth." (PMID 28281543, 2017). "Egfr/Arf6-triggered Hh signalling thus synergizes with oncogenic Ras to cause tumour overgrowth." (PMID 28281543, 2017). "Thus, the cooperation between eIF4A/4E-dependent mRNA translation and MVP has been identified as a link in which representative pancreatic driver mutations empower an ARF6-based pathway, activated by external ligands, to promote tumor cell motility, PD-L1 dynamics, and immune evasion." (PMID 36408139, 2022). "ARF6 is frequently overexpressed in cancers such as lung, breast, prostate, and colon, and its activation is associated with increased tissue invasion and increased formation of invadopodia and tumor-derived microvesicles to facilitate movement through the extracellular matrix." (PMID 27589803, 2016). "Herein, we discovered that the small GTPase ARF6 plays a central role in tumor survival by fortifying RAF oncoprotein levels." (PMID 42050077, 2026). "In contrast, EIPA or NAV2729 treatment slowed tumor growth on the left side (EV receiver) compared to Ctrl, confirming that Arf6-driven macropinocytosis promotes SFR." (PMID 41362734, 2026). "Previous research has indicated that ARF6 has a significant impact on tumor proliferation, angiogenesis, invasion, metastasis, and immune evasion." (PMID 40270615, 2025). "With longer treatments (14 days), Dab + Tram reduced tumor colony formation, however, a low level of resistant tumor colonies persisted, and this was significantly diminished by knockdown of ARF6." (PMID 40909781, 2025). "Analysis of TCGA data reported that ARF6 expression is significantly elevated in several tumor types, including AML." (PMID 40275490, 2025). "In PDAC, tumor- and nerve-derived Sema3D reprogram macrophages indirectly via KRAS mutation-dependent adenosine diphosphate-ribosylation factor 6 (ARF6) signaling in tumor cells." (PMID 41163091, 2025). "Herein, we discovered that when activated, the small GTPase ARF6 plays a central role in tumor survival by facilitating expression of the BRAFV600E oncoprotein." (PMID 40909781, 2025).
tumor (continued). "A study on the inhibition of metastasis in CRC cells revealed that the invasive ability of tumor cells decreased upon ARF6 inhibition; conversely, it increased when ARF6 was overexpressed." (PMID 40270615, 2025). "By interrogating ARF6 in vitro and in immunodeficient mice, we removed the influence of adaptive immunity and discovered an unanticipated role for ARF6 in tumor cell survival." (PMID 40909781, 2025). "Tumor-specific Arf6 deletion caused a significant reduction in BRAFV600E protein and MAPK signaling and prevented rapid tumor progression." (PMID 40909781, 2025). "More work is needed to understand ARF6-mediated tumor survival, including during immune-mediated tumor killing." (PMID 40909781, 2025). "Binding of circ0001955 to miR-145-5p abolishes its tumor suppressor activity, thereby derepressing ARF6 and SPATS2." (PMID 41465470, 2025). "ARF6 was also discovered to play important roles in loading pre-miRNA and DNA cargo to microvesicles shed from tumor cells." (PMID 39204374, 2024). "Oncosomes, 1–5 μm microvesicles released from tumor cells due to oncoprotein overexpression, also characterized by ARF6 and annexin A1 expression." (PMID 39204374, 2024). "Inhibiting GGT-II not only suppressed tumor invasion and metastasis, but also diminished resistance to chemotherapeutic drugs in tumor cells that overexpress components of the ARF6 pathway." (PMID 39682280, 2024). "We estimated the effect of ARF6 on tumor proliferation with in vitro CCK8, colony formation assay, and in vivo nude mouse xenograft models." (PMID 37716993, 2023). "ARF6, in particular, is involved in the regulation of actomyosin contractile machinery, but also ARF6-positive endosomes serve as a repository for tumor MV-specific cargo, such as β1-integrin and membrane type 1 (MT1)-MMP." (PMID 37760395, 2023). "Arf6 controls cytoskeletal remodeling, cell shape alterations, extracellular matrix proteolysis, and cell adhesion mechanisms involved in tumor cell migration." (PMID 37081847, 2023). "The inhibition of GGT-II not only blocked tumor invasion and metastasis, but also reduced tumor cell resistance to chemotherapeutic agents in cells overexpressing components of the ARF6-based pathway." (PMID 37834383, 2023). "The increased expression of ARF6 correlated with poor tumor differentiation, incomplete tumor encapsulation, advanced tumor TNM stage and poor prognosis." (PMID 37716993, 2023). "We found that ARF6 level was significantly elevated in tumor tissues in comparison with corresponding adjacent non-tumor tissues." (PMID 37716993, 2023). "ADP-ribosylation factor 6 (Arf6) can be activated via nucleotide exchange by guanine-nucleotide-exchange factors (GEFs), and its activation also regulates tumor invasion and migration." (PMID 36017701, 2022). "For instance, ARF6 is responsible for the packaging of vesicle associated membrane protein (VAMP3), integrin β-1, and MHC I into tumor-cell derived MVs, as well as the simultaneous exclusion of transferrin receptors." (PMID 36045692, 2022). "In model mice treated with AR decoction or Oxaliplatin, the weight of the tumor was significantly reduced, and the protein levels of Wnt 5, β-Catenin, ARF6 and N-Cadherin in the tumor were significantly down-regulated." (PMID 34991661, 2022). "Previous studies demonstrated that ARF6 plays important roles in tumor proliferation, angiogenesis, invasion, and metastasis." (PMID 35140331, 2022). "Signaling pathways regulated by the small Ras-related GTPases (ARF6 and Rho family) are thought to govern the formation and release of tumor-derived MVs." (PMID 35586060, 2022).
tumor (continued). "For example, ARF6, which has been shown to regulate shedding of tumor-derived plasma membrane microvesicles, was only significantly enriched in lEVs compared with sEVs from the D3H1 cells." (PMID 35918030, 2022). "We then explored the role of ARF6 in tumor growth and found that knocking down ARF6 significantly inhibited the proliferation of WT EGFR cells, A549 cells, and MDA-MB-231, as well as EGFR mutant cells, PC9 and H1975 cells." (PMID 36224181, 2022). "Knocking down ARF6 blocks EGFR sorting to PM, causes degradation of EGFR, disrupts EGF-induced EGFR signaling, and inhibits the growth of EGFR-overexpression tumor cells." (PMID 36224181, 2022). "Depletion of ARF6 partially abolished tumor cells migration, invasion and metastasis driven by DDR1 overexpression with collagen I." (PMID 35140331, 2022). "Altogether, these results indicate that DUSP6 plays a tumor-suppressive role and acts as an intermediate molecule between ARF6 and ERK1/2 in PDAC cells, thereby forming a positive feedback loop." (PMID 36017891, 2022). "In fact, MDA-MB-231 and A549 cells used in our experiments also bear KRas mutations, and we show that knockdown of either EGFR or ARF6 inhibits tumor growth." (PMID 36224181, 2022). "Previous studies suggested that ARF6, as a master driver of tumorigenesis and tumor progression, activates several important signaling pathways." (PMID 34621682, 2021). "To further investigate the effects of the lncRNA MDFIC-7/miR-525-5p/ARF6 axis on tumorigenicity in vivo, we generated a xenograft tumor mouse model using U-CH1 cells infected with lentivirus to downregulate lncRNA MDFIC-7." (PMID 34621682, 2021). "In summary, Arf6 would control cell motility, invasion and metastasis, whereas Arf1 would be involved in tumor cell growth." (PMID 33673086, 2021). "Deletion of Arf6 in endothelial cells abolishes hepatocyte growth factor-stimulated β1 integrin recycling, and pharmacological inhibition of the Arf6-GEF suppresses tumour angiogenesis and growth." (PMID 32322163, 2020). "Arf6, which is located in mitotic intermediates, can participate in the regulation of mitotic activity as well as tumor cell growth and proliferation." (PMID 32822124, 2020). "ARF6 is well characterized in the context of cancer and known to regulate cancer cell invasion and metastasis, as well as tumor angiogenesis and growth." (PMID 32426352, 2020). "Tumor MVs contain complexes of ARF6/XPO5 and pre-miRs; translocation of XPO5 to the MVs involve a complicated interaction involving CK2, RAN and cytohesion family guanine exchange factors." (PMID 39698114, 2020). "A number of studies have demonstrated the anti-tumor activity of statins via a variety of mechanisms, including inhibition of RhoA, NF-κB, Arf6 or PI3K signaling." (PMID 32541798, 2020). "Here, we identify ADAP1, a GTPase-activating protein (GAP) for ARF6 up-regulated in TGF-β-responding invasive tumor cells, as a strong predictor of poor survival in early-stage SCC patients." (PMID 31792062, 2019). "For this, tumor cells were isolated from the primary tumor lesions and were cultured in vitro, and then transduced with shRNA to silence Amap1 and Arf6." (PMID 29329590, 2018). "At the metastatic sites, ubiquitous expression of AMAP1 was observed in most cases, whereas the expression of Arf6 demonstrated regional variations even within the same tumor lesions both in PyMT- and Neu-tumors." (PMID 29329590, 2018). "We conclude that in both Drosophila and human cells, Arf6 has a critical role in the growth of Ras mutant tumours." (PMID 28281543, 2017). "We investigated a role for Arf6 in oncogenic Ras tumour overgrowth and found that Egfr promotes Arf6 to interact with Hh." (PMID 28281543, 2017). "We have recently reported that Arf6 expressed in VECs plays an important role in tumor angiogenesis and cancer progression: ablation of Arf6 from mouse vascular endothelial cells (mVECs) inhibits tumor angiogenesis, therefore suppressing tumor growth." (PMID 28900118, 2017).